TNF (tumor necrosis factor)
Diseases named in the same sentence as TNF in open-access papers (continued):
Sharing a sentence is not in itself a finding about the gene and the disease.
atherosclerosis (continued). "Additionally, it could be shown that PCSK9 aggravates atherosclerosis in apolipoprotein-E deficient mice, which was associated with an increased expression of inflammatory cytokines such as TNF-α, IL-1β, IL-10, MCP-1, and IL-8 to directly facilitate the process of inflammation." (PMID 34884827, 2021). "TNF-α plays an essential role in developing atherosclerosis by promoting adhesion molecules’ expression on endothelial cells, inducing some critical inflammatory mediators and initiating the inflammatory cascade." (PMID 34300308, 2021). "The dominant role of the p38 MAPK/NF-κB signalling pathway in mediating TNFα-induced cytokine/chemokine synthesis, endothelial cell dysfunction and cellular molecular adhesion expression in atherosclerosis has been convincingly demonstrated." (PMID 34502180, 2021). "In contrast, Th1 lymphocytes promote atherosclerosis by exuding proinflammatory components such as interferon-γ and TNF-α." (PMID 34201137, 2021). "EC inflammation is the early event in the pathogenesis of atherosclerosis, and OSS can activate EC pro-inflammatory responses by triggering the release of signaling molecules such as TNF-α to promote atherosclerosis progression." (PMID 34262908, 2021). "Despite the acknowledged role of TNF-α in atherosclerosis development and progression, the mechanisms that regulate TNF-α expression in patients with SCAD are not fully understood." (PMID 34199767, 2021). "Proinflammatory cytokines including TNF-α, IL-1β, IL-6 are also a mediator of atherosclerosis since they activate endothelial cells, attract monocytes, and facilitate their adhesion by up-regulating MCP-1, ICAM, VCAM." (PMID 34885795, 2021). "The TNFα signaling pathway is a central pro-inflammatory pathway involved in atherosclerosis progression." (PMID 34944413, 2021). "Exosomes from mature dendritic cells (DCs) are involved in increasing endothelial inflammation and atherosclerosis via the NF-κB pathway mediated by tumor necrosis factor-α (TNF-α) located in the exosome membrane." (PMID 34456875, 2021). "The result of the enrichment gene dataset analysis indicated that the genes significantly enriched were involved in the TNF signaling pathway, MAPK signaling pathway, fluid shear stress, atherosclerosis, and Kaposi’s sarcoma-associated herpesvirus infection." (PMID 34163322, 2021). "In atherosclerosis rabbit models, paeonol intervention decreased atherosclerotic plaques and normalized serum levels of tumor necrosis factor (TNF)-α, interleukin (IL)-1β, and C-reaction protein (CRP)." (PMID 34368250, 2021). "For instance, tumor necrosis factor-alpha (TNFα), interleukin (IL)-6, and IL-17 have a direct contribution to joint damage and to the development of accelerated atherosclerosis and premature CVE." (PMID 33195306, 2020). "Further, TNF-α is a well-known inflammatory marker, besides being related to atherosclerosis in males." (PMID 32545460, 2020). "PAA increased reactive oxygen species (ROS) and tumor necrosis factor (TNF)α release in vascular endothelial cells, which are known to contribute to atherosclerosis and blood vessel calcification." (PMID 32545914, 2020). "Of these, cluster 1 mainly included AGE-RAGE signaling pathway in diabetic complications (p = 5.30E−25), fluid shear stress and atherosclerosis (p = 7.46E−19), TNF signaling pathway (p = 6.04E−15), and IL-17 signaling pathway (p = 1.30E−14)." (PMID 33134394, 2020). "In animal models, dietary supplemented POA decreased the expression of pro-inflammatory cytokines TNF-α and IL-6 and reduced atherosclerosis development." (PMID 33348748, 2020). "The GSEA results demonstrated that the enriched pathways generally involved inflammation and immune response pathways, such as cytokine–cytokine receptor interaction, atherosclerosis, and TNF signaling." (PMID 33195475, 2020).
atherosclerosis (continued). "To mimic the inflammatory status of AoSMCs during atherosclerosis, we treated the cells with TNFα, a pleiotropic cytokine that mediates vascular SMC migration and proliferation." (PMID 31932306, 2020). "In laboratory models, PAPP-A expression increases in damaged vessels and human plug atherosclerosis by stimulation of Tumor Necrosis Factor (TNF) and Interleukin-1 beta." (PMID 32500016, 2020). "As critical examples, when compared with control animals, TNF-α and Apo E double-knockout mice have less atherosclerosis and reduced endothelial adhesion; an effect replicated in ApoE mice treated with agents that reduce TNF-α activity." (PMID 33025148, 2020). "Atherosclerosis is characterized by low-grade chronic inflammation in the vasculature with elevated levels of inflammatory cytokines such as TNF-α." (PMID 33239628, 2020). "Primary proinflammatory cytokines produced by macrophages during atherosclerosis initiation and development are IL-1β, IL-6, TNFα, and CCL2." (PMID 33374145, 2020). "The body weight, TC, LDL-C, HDL-C, AI, WBC counts, as well as CRP and TNF-α levels, were significantly increased in the atherosclerosis group compared to the NC group (P < 0.05, P < 0.01), except for TG." (PMID 32213192, 2020). "It shows antioxidant properties against LDL-oxidation, thus potentially preventing atherosclerosis, and anti-inflammatory properties by decreasing the expression of TNF-α, interleukins IL-6 and IL-1b in a mouse macrophage cell line." (PMID 33237940, 2020). "Apremilast also inhibited the expression of tumor necrosis factor-α (TNF-α), interleukin-6 (IL-6), and interleukin-8 (IL-8), which are deeply involved in the chronic inflammatory response associated with atherosclerosis." (PMID 33052879, 2020). "TNF-α is a proinflammatory cytokine, which has an important role in the pathogenesis of atherosclerosis." (PMID 32327953, 2020). "The overexpression of TNF-α was an early key event in atherosclerotic lesions and was related to a severe degree of atherosclerosis and thickening of vascular intima." (PMID 33029103, 2020). "IL-1β, IL-6, IL-18, c-reactive protein (CPR), tumor necrosis factor α (TNF-α), etc., as important proinflammatory factors in the process of atherosclerosis, play an important role in promoting the formation of atherosclerosis." (PMID 32733941, 2020). "In atherosclerosis, mechanistic studies identify TNF-α as a fundamental driver of impaired AC removal, accounting for the activation of NF-κB and a compromised role of defective efferocytosis in vascular disease." (PMID 32346605, 2020). "TNF-α expression promoted the atherosclerosis development and thickening of vascular intima and played a key role in human atherogenesis." (PMID 33029103, 2020). "The interaction between monocytes and endothelial cells through VCAM-1 expression induced by TNF-α is important for atherosclerosis development." (PMID 32218307, 2020). "The cytokines contributing to atherosclerosis can be broadly divided into proatherogenic (such as IL-1β, IL-6, TNF-α) and antiatherogenic (such as IL-10 and IL-1rA)." (PMID 32485823, 2020). "These EOs are potentially useful in the management of inflammatory diseases mediated by CCL2 and TNF‐α, such as atherosclerosis and arthritis." (PMID 33379375, 2020). "Gene sets related to atherosclerosis signaling, primary immunodeficiency, IL-17, and TNF signaling pathways were differentially activated in AMI compared with the control." (PMID 33195475, 2020). "Through perfusion of enzyme-modified LDL, TNFα and monocytes in this system, the disease model of early stage atherosclerosis was established in vitro." (PMID 33110060, 2020). "Activation of the TLR signaling pathway lead to the production of multiple pro-inflammatory cytokines (IL-6, TNF-α), accelerating the pathological process of atherosclerosis." (PMID 33425996, 2020).
atherosclerosis (continued). "Data obtained from bone marrow chimeric mice suggested that TNF-α expressed by the bone marrow cells played a key role in an Apoe−/− mouse model of atherosclerosis." (PMID 33053859, 2020). "Cytokines play a key role in inflammatory diseases and a link with hypercholesterolemia and atherosclerosis has emerged mainly for the IL-6, IL-1, and TNFα pathways." (PMID 32849284, 2020). "Atherosclerosis is a chronic inflammatory condition with elevated levels of inflammatory cytokines, such as tumor necrosis factor-α (TNF-α) and interleukin-1β (IL-1β), secreted by activated ECs and macrophages within atherosclerotic lesions." (PMID 32455571, 2020). "Upon infiltration, macrophages are activated by OxLDL and subsequently secrete inflammatory cytokines, such as TNF-α and IL-6, enhancing the progression of atherosclerosis." (PMID 32752134, 2020). "Our findings are in line with previous research and further confirm the systemic effects of CCL4 antibody treatment on circulating IL-6 and TNF-α in in vivo experimental atherosclerosis." (PMID 32911750, 2020). "Mechanistically, the anti-AS effect of PNS was exerted by interfering with multiple signaling pathways, such as AGE-RAGE signaling pathway, fluid shear stress and atherosclerosis, and TNF signaling pathway." (PMID 32382308, 2020). "The GSEA results demonstrated that the enriched pathways mainly involved cytokine–cytokine receptor interaction, atherosclerosis, IL-17 signaling pathway, primary immunodeficiency, and TNF signaling pathways." (PMID 33195475, 2020). "Among these pathways, the top three were fluid shear stress and atherosclerosis, TNF signaling pathway, and IL-17 signaling pathway based on the number of the pathway target genes." (PMID 32908565, 2020). "Inflammation and dysfunction in endothelial cells and VSMCs, which can be induced by TNF-α, play an important role in vascular homeostasis and atherosclerosis progression exacerbation and represent the initial events of atherosclerosis." (PMID 32218307, 2020). "The overexpression of TNF-α was an early key event in atherosclerotic lesions and was related to a severe degree of atherosclerosis." (PMID 33029103, 2020). "NF-kB, SIRT1 and systemic inflammation factors including hs-CRP, IL-6 and TNF-α accelerate atherosclerosis pathogenesis." (PMID 31901246, 2020). "TNF-α is the main cytokine involved in the pathogenesis of RA, which can lead to atherosclerosis and endothelial dysfunction." (PMID 33072123, 2020). "In macrophages, oxLDL has been shown to provoke the massive release of TNF-α, a potent proinflammatory cytokine that is involved in the progression of atherosclerosis." (PMID 32635347, 2020). "In the contest of atherosclerosis, researchers measured adhesion molecules expression in primary ECs after TNF-α treatment, which mimicked atherosclerosis inflammation condition." (PMID 32887493, 2020). "We focus on the contribution of cytokine networks encompassing IL-4, IL-6, IL-9, IL-17A, IL-33 but also IFN-γ and TNF-α to vascular dysfunction in atherosclerosis." (PMID 32194407, 2020). "Briefly, as atherosclerosis progresses, increased secretion of tumor necrosis factor (TNF)-α and IL-1 induces production of IL-6 in activated monocytes and vascular smooth muscle cells, which enhances hepatic CRP synthesis." (PMID 32433661, 2020). "Related with this process, it has been observed that TNF-α plays a key role in the development of atherosclerosis, being predominately expressed in early atherosclerotic lesions." (PMID 32899258, 2020). "Our study showed, in addition to possessing benefits to serum lipids, HLP can effectively decrease serum LDL/HDL ratio and TNF-α level, thus improving atherosclerosis." (PMID 31817413, 2019). "IL-6 and TNF-α can also induce the production of suPAR from monocytes and lymphocytes, which has a well-established role in the development of atherosclerosis." (PMID 30820636, 2019).
atherosclerosis (continued). "In the atherosclerosis + vector group, serum levels of TNF-α and IL-1β significantly increased (P < 0.01), whereas the serum level of TGF-β1 significantly decreased (P < 0.05), as compared with the control group." (PMID 31781638, 2019). "A number of cytokines, including TNFα, induce the extracellular matrix glycoprotein, TNC, associated with the pathogenesis of atherosclerosis and foam cell formation." (PMID 31969876, 2019). "The proliferation and migration of vascular smooth muscle cells (VSMCs) are major events in the development of atherosclerosis following stimulation with proinflammatory cytokines, especially tumor necrosis factor-alpha (TNF-α)." (PMID 31817413, 2019). "IL-1 and TNF-a can induce the binding of low-density lipoprotein (LDL) to vessel walls and the deposition of blood lipids, which causes atherosclerosis at early stages of cardiovascular disease." (PMID 31035622, 2019). "During atherosclerosis progression, inflammatory cytokines, such as interleukin-1β (IL-1β) and tumor necrosis factor α (TNFα), are involved in vascular remodeling." (PMID 31735914, 2019). "Other early inflammatory biomarkers for atherosclerosis include TNF-α, found useful in predicting CV events in the short term, as well as molecules involved in the initial phases of cell interaction and atheroma formation." (PMID 31354915, 2019). "TNF-α has been shown to be involved in the pathogenesis of atherosclerosis since it promotes the recruitment of inflammatory cells and blood vessel remodeling." (PMID 31717327, 2019). "The uncontrolled TNF-α and IL-6 production lead to metabolic disorders such as type 2 diabetes and atherosclerosis." (PMID 30909606, 2019). "Similar to the function of IL-6, TNF-α is also a pro-atherosclerotic cytokine and increases the development of atherosclerosis in several ways." (PMID 31616435, 2019). "Studies also demonstrated that vascular autophagy is present in atherosclerosis and is regulated by tumor necrosis factor-alpha and insulin-like growth factor-1." (PMID 31467666, 2019). "During atherosclerosis, pro-inflammatory cytokines such as TNF-α and IL-6 both have been related to vascular inflammation." (PMID 31780924, 2019). "al. reported that B2-derived TNFα promoted atherosclerosis by augmenting TNFα production via lesion macrophages." (PMID 31206525, 2019). "Its activation triggers inflammatory cytokines (such as MCP-1, IL-1β, and TNF-α) production and release, which results in inflammatory cascade and thereby promotes atherosclerosis." (PMID 30881312, 2019). "The present study investigated the involvement of Chlamydia trachomatis and Chlamydia pneumoniae infections and immunological markers (C-reactive protein, CRP, TNF-α, IL-6, IL-8, and IL-10) in the process of atherosclerosis." (PMID 30804931, 2019). "It has been known to block the expression of vascular adhesion molecule in TNF-α-stimulated VSMCs, alleviate apoptosis of endothelial cells, and prevent the onset of atherosclerosis." (PMID 31212679, 2019). "Both cytokines are involved in atherosclerosis progression in mice as TNFα promotes atherosclerosis and IL-1β knockout mice have smaller and less severe atherosclerotic lesions." (PMID 31461490, 2019). "Expression of the pro-inflammatory cytokines, TGF-β, tumor necrosis factor α (TNFα), IL-1β, and IL-6 is consistently observed in atherosclerosis and AVS." (PMID 31510085, 2019). "Previous studies have reported that inflammatory markers such as TNF-α and IL-1βwere increased in atherosclerosis." (PMID 31998222, 2019). "In the Atherosclerosis + Overexpression group, serum levels of TNF-α and IL-1β significantly increased (P < 0.01), whereas serum level of TGF-β1 significantly decreased (P < 0.05), as compared with the Atherosclerosis + Vector group." (PMID 31781638, 2019). "PTX3 is stored in neutrophil granules on areas of atherosclerosis and released when neutrophils are exposed to TNF-α." (PMID 31998222, 2019).
atherosclerosis (continued). "In the early stage of atherosclerosis, ginsenoside Rb1 promoted anti-atherosclerotic effects, reducing the production of inflammatory cytokines including TNF-α, IL-1β, and IL-6." (PMID 30744138, 2019). "The mouse phenotypes also confirm that the modules contain attractive CAD drug target candidates, as many of the genes have a driver role for atherosclerosis (e.g. TNF and FN1) (for more details and references see69)." (PMID 29467471, 2018). "Our discovery that, during M. tuberculosis infection, TNFα signaling contributes to the accumulation of a different class of storage lipid than reported previously with atherosclerosis establishes the novelty of the work." (PMID 30161232, 2018). "Several lines of evidence support the crucial involvement of TNF-α in the pathogenesis of atherosclerosis." (PMID 30524759, 2018). "Although circulating levels of anti-TNFα and anti-IL1α IgG antibodies were significantly increased in atherosclerosis, ROC curve analysis revealed relatively low sensitivity." (PMID 30479572, 2018). "Plasma anti-TNFα-1 IgG levels were significantly higher in patients with atherosclerosis patients than control subjects (t = 3.588, p < 0.001), female patients mainly contributing to increased anti-TNFα-1IgG levels in atherosclerosis (t = 3.810, p < 0.001)." (PMID 30479572, 2018). "TNFα is also involved in endothelial cell injury under pathological conditions, such as atherosclerosis." (PMID 30029641, 2018). "In turn, a sustained increase in the level of IL-6 and TNF-α favors the hepatic release of acute-phase reactants including CRPs, critically involved in PsA, CPs, and atherosclerosis." (PMID 29535705, 2018). "Several inflammatory cytokines, such as TNF-α, IL-1β and IL-6, have been shown to induce VSMCs proliferation/migration and hypertrophic response, which can contribute to the development of atherosclerosis." (PMID 29728095, 2018). "Macrophages are a major driver of pathogenesis in atherosclerosis, by secreting inflammatory cytokines, such as TNF-α and interleukin-1β (IL-1β), and making communication with other immune cells, such as Th1 cells." (PMID 29760701, 2018). "It is well established that TNF-α plays a key role in the atherosclerosis process through stimulation of the TH1 pathway, thus leading to macrophage activation." (PMID 29337902, 2018). "In this study, the gender differences in circulating IgG antibodies to inflammatory cytokines were observed, so that up-regulation of anti-TNFα, anti-IL1α, and anti-IL1β IgG levels were more likely to occur in female than male patients with atherosclerosis." (PMID 30479572, 2018). "The visceral adipose tissue secretes several adipocytokines, such as adiponectin, leptin, and tumor necrosis factor-α (TNF-α), which has been proved to reduce or increase atherosclerosis." (PMID 29619063, 2018). "In this study, we found that plasma anti-TNFα and anti-IL1α IgG levels were significantly increased in patients with atherosclerosis compared with control subjects, and an increase in anti-IL1β IgG level was found in female patients." (PMID 30479572, 2018). "Upregulation of IL-10 expression with a concomitant decrease in the production of TNF-α and IL-18 was put forward as a direct anti-inflammatory mechanism of IL-37 mediated amelioration of atherosclerosis and CAC." (PMID 29641433, 2018). "Released HMGB1 interacts with RAGE, one of the main signaling pathways triggered in sustained inflammatory related diseases, and TNF-α is a potent pro-inflammatory cytokine that can induce atherosclerosis." (PMID 29561847, 2018). "In atherosclerosis, Th cells respond to the Th1 type, which secretes large amounts of IFN-γ and TNF-α, mediating macrophage activation, and promoting atherosclerosis development and plaque enlargement." (PMID 30142970, 2018). "In atherosclerosis model mice, the IL-6 and TNF-α level were significantly increased in plasma and aortic tissues when p-STAT3 levels were increased." (PMID 30142970, 2018).